PCNA (proliferating cell nuclear antigen)
Description:
Confers DNA tethering and processivity to DNA polymerases and other proteins. Auxiliary protein of DNA polymerase delta and epsilon, is involved in the control of DNA replication by increasing the polymerases' processivity during elongation of the leading strand. Induces a robust stimulatory effect on the 3'-5' exonuclease and 3'-phosphodiesterase, but not apurinic-apyrimidinic (AP) endonuclease, APEX2 activities. Has to be loaded onto DNA in order to be able to stimulate APEX2. Plays a key role in DNA damage response (DDR) by being conveniently positioned at the replication fork to coordinate DNA replication with DNA repair and DNA damage tolerance pathways. Acts as a loading platform to recruit DDR proteins that allow completion of DNA replication after DNA damage and promote postreplication repair: monoubiquitinated PCNA leads to recruitment of translesion (TLS) polymerases, while 'Lys-63'-linked polyubiquitination of PCNA is involved in error-free pathway and employs recombination mechanisms to synthesize across the lesion.
Synonyms: ATLD2
Tractability: Small molecule: a structure with a bound ligand is known; a high-quality ligand is known. PROTAC: it is named in the literature on targeted protein degradation; UniProt records ubiquitination sites on it; ubiquitination databases record sites on it; its protein half-life has been measured; a small molecule that binds it is known.
Target class: Other nuclear protein
Gene: Protein-coding gene on chromosome 20 (5,114,953 to 5,126,626, reverse strand). Ensembl gene ENSG00000132646.
Subcellular location: Nucleus
Subcellular location (Human Protein Atlas): Nucleoplasm
Pathways (Reactome):
DNA Repair: Dual Incision in GG-NER; Dual incision in TC-NER; Gap-filling DNA repair synthesis and ligation in GG-NER; Gap-filling DNA repair synthesis and ligation in TC-NER; HDR through Homologous Recombination (HRR); PCNA-Dependent Long Patch Base Excision Repair; Recognition of DNA damage by PCNA-containing replication complex; Termination of translesion DNA synthesis; Translesion Synthesis by POLH; Translesion synthesis by POLI; Translesion synthesis by POLK; Translesion synthesis by REV1
Cell Cycle: G1/S-Specific Transcription; Polymerase switching on the C-strand of the telomere; Processive synthesis on the C-strand of the telomere; Removal of the Flap Intermediate from the C-strand; Telomere C-strand (Lagging Strand) Synthesis; Transcription of E2F targets under negative control by DREAM complex
DNA Replication: Polymerase switching; Processive synthesis on the lagging strand; Removal of the Flap Intermediate
Metabolism of proteins: E3 ubiquitin ligases ubiquitinate target proteins; SUMOylation of DNA replication proteins
Gene Ontology:
Molecular function: chromatin binding; damaged DNA binding; dinucleotide insertion or deletion binding; DNA polymerase binding; enzyme binding; histone acetyltransferase binding; identical protein binding; MutLalpha complex binding; protein binding; protein-containing complex binding; purine-specific mismatch base pair DNA N-glycosylase activity; receptor tyrosine kinase binding; DNA polymerase processivity factor activity; DNA binding; nuclear estrogen receptor binding
Biological process: chromatin organization; DNA repair-dependent chromatin remodeling; epithelial cell differentiation; mismatch repair; mitotic DNA replication; positive regulation of DNA repair; positive regulation of DNA replication; translesion synthesis; leading strand elongation; mitotic telomere maintenance via semi-conservative replication; replication fork processing; cellular response to hydrogen peroxide; cellular response to UV; estrous cycle; heart development; liver regeneration; regulation of DNA replication; response to cadmium ion; response to dexamethasone; response to estradiol; response to L-glutamate; response to lipid; response to oxidative stress
Cellular component: centrosome; chromatin; chromosome, telomeric region; extracellular exosome; nuclear replication fork; nucleoplasm; nucleus; PCNA complex; PCNA-p21 complex; replication fork; replisome; cyclin-dependent protein kinase holoenzyme complex; nuclear lamina
Genetic constraint (gnomAD): Loss-of-function variants: 4 observed, 21.82 expected, observed/expected ratio (o/e) 0.18, 90% interval 0.089 to 0.42. The upper end of that interval is the gene's LOEUF score, 0.42, which puts it in group 1 of 6, group 1 being the genes least tolerant of losing a copy. Missense variants: 161 observed, 319.27 expected, observed/expected ratio (o/e) 0.5, 90% interval 0.44 to 0.57. Synonymous variants: 119 observed, 117.27 expected, observed/expected ratio (o/e) 1.01, 90% interval 0.87 to 1.18.
Gene-disease validity (ClinGen):
ClinGen rates the evidence that PCNA causes each of these diseases.
hereditary ataxia (autosomal recessive): Limited. An instance of an atactic disorder that is caused by an inherited genomic modification in an individual.
Homologues: Orthologues: chimpanzee PCNA (100% identical), macaque PCNA (100% identical), dog PCNA (99% identical), pig PCNA (99% identical), rabbit PCNA (99% identical), guinea pig PCNA (99% identical), rat Pcna (98% identical), mouse Pcna (97% identical), zebrafish pcna (91% identical), tropical clawed frog pcna (90% identical), Drosophila melanogaster PCNA (69% identical), Caenorhabditis elegans pcn-1 (46% identical), and 1 more.
Diseases named in the same sentence as PCNA in open-access papers:
PCNA is named in the same sentence as 457 diseases in open-access papers, as found by Europe PMC text mining. Sharing a sentence is not in itself a finding about the gene and the disease. The quoted sentences say what the papers report.
breast cancer (211 papers, 2003 to 2026). A primary or metastatic malignant neoplasm involving the breast. "This modification partially stabilizes chromatin-associated PCNA, thereby promoting cancer cell proliferation, particularly in breast cancer." (PMID 41024300, 2025). "An overexpression of PCNA has been observed in various malignancies, including breast cancer, and is often associated with increased tumor aggressiveness and poor prognosis." (PMID 40430573, 2025). "This study provides initial evidence supporting the potential of skimmianine to modulate tumor proliferation and immune dynamics in breast cancer through PCNA- and TNF-α-associated mechanisms." (PMID 40430573, 2025). "They concluded that removing the effects of meta-PCNA genes on the expression of the genes in the NKI breast cancer dataset cohort was a perfect way to reduce the association between random genes and survival." (PMID 37248269, 2023). "Breast cancers with high PCNA scores (≥25) have been associated with shorter disease-free (p = 0.007) and overall survival (p = 0.01) times." (PMID 37511298, 2023). "In breast cancer, proliferating TAMs were identified by proliferating cell nuclear antigen (PCNA) and found to be associated with tumor progression and poor prognosis." (PMID 33144684, 2021). "Consistently, systemic CXCR2 KO mice decreased PCNA and F4/80 tumor associated Mφ in mammary tumors." (PMID 34638514, 2021). "In agreement, our results indicated that MET increased the level of p‐APMK in drug‐resistant and drug‐sensitive breast cancer cells, and also reduced the levels of other proteins associated with cell proliferation (cyclin D1 and PCNA)." (PMID 32281270, 2020). "A peptide spanning the IDCL (126–133aa) was shown to reduce PCNA association with chromatin and exert cytotoxic effect on breast cancer, lymphoma, and pancreatic cancer cell lines." (PMID 30126151, 2018). "The PCNA signal transduction has an important impact on growth regulation of breast cancer cells and is associated with poor overall survival." (PMID 24591761, 2014). "Adjusting breast cancer expression data for meta-PCNA abrogated almost entirely the outcome association of published and random signatures." (PMID 22028643, 2011). "Upregulation of PCNA in breast cancers is associated with poor prognosis." (PMID 37511298, 2023). "Therefore, a second aim of this study was to explore the association of PCNA+ TAMs, the tumor immune microenvironment, and outcomes in women with breast cancer treated with neoadjuvant chemotherapy." (PMID 24205370, 2013). "This, along with the observation that PCNA+ TAMs were associated predominantly with M1-related genes, may provide new insights into the role of the immune microenvironment in breast cancer." (PMID 24205370, 2013). "The proteomic comparisons notably led to the identification of five proteins that are used as breast cancer diagnostic and prognostic biomarkers: proliferating cell nuclear antigen (PCNA), cathepsin D, cathepsin B, protein S100-A14, and heat shock protein beta-1 (HSP27)." (PMID 22384035, 2012). "High expression of PCNA is associated with poor prognosis in patients with breast cancer." (PMID 18949048, 2008). "Similar ceRNA networks involving SNHG5 have been reported in other malignancies, including the SNHG5–miR-154-5p–PCNA axis in breast cancer and the SNHG5–miR-26a-5p–GSK3β axis in HCC." (PMID 41550840, 2026). "The results showed significant associations, with both PCNA and TNF-α exhibiting a higher expression in the basal subtype of breast cancer (p < 0.05)." (PMID 40430573, 2025). "2α-Hydroxyursolic acid has been shown to inhibit the expression of PCNA in breast cancer cells, exerting anticancer activity by regulating the p38/MAPK signaling pathway." (PMID 41024300, 2025).
breast cancer (continued). "CDK2, PCNA, CXCL8, and E2F1 were involved in the cell cycle, and were associated with worse survival for breast cancer." (PMID 40697521, 2025). "As an important marker of cell proliferation, PCNA promotes cancer cell division and breast cancer development, while also inhibiting apoptosis, thereby facilitating tumor progression." (PMID 40697521, 2025). "In one study comparing pre- and post-menopausal breast cancer patients, PCNA showed higher expression in the post-menopausal group and a significant correlation with HER-2/neu expression in the same group." (PMID 40940954, 2025). "Increased PCNA expression has been linked to a poor prognosis in breast cancer patients, and EGFR TKI-resistant breast cancer cells show elevated PCNA expression." (PMID 40560045, 2025). "In this study, we investigated its effects on breast cancer by evaluating PCNA and TNF-α expression and analyzing their molecular and immunological associations using in silico approaches." (PMID 40430573, 2025). "It was found that Hispanic women had a higher PCNA+ TAM count in breast cancers and decreased recurrence-free survival compared to Caucasian women." (PMID 39205238, 2024). "Microscopic analysis of the mammary tumor tissues using PCNA immunohistochemistry as a proliferative marker revealed a high rate of proliferation of tumor cells in the DMBA-induced mammary tumor compared to the control mammary tissue." (PMID 39734347, 2024). "Paraffin sections obtained from the mammary tumor tissue were subjected to hematoxylin-eosin, toluidine blue staining, and proliferating cell nuclear antigen (PCNA) immunohistochemistry." (PMID 39734347, 2024). "A signature performed by four of these hub nodes (CDK1, PCNA, EZH2, and BUB1) was associated with relapse events in untreated luminal breast cancer patients." (PMID 38831458, 2024). "These genes, along with other observed central nodes as PCNA, participate in various cellular processes in breast cancer, encompassing the regulation of the cell cycle, DNA replication, and cell division." (PMID 38831458, 2024). "Of these, CCNE2 and PCNA have been identified as key targets of KCNQ1OT1 regulators for promoting cell proliferation in breast cancer and glioma." (PMID 38361755, 2024). "Meanwhile, exogenous miR-186-5p mimic in MDA-MB-231 cells significantly inhibited the expression of SBEM, p-PI3K, p-AKT and their downstream pathways, MMP1, MMP3, MMP9, CyclinD1, PCNA and CyclinB1 proteins and reduced proliferation of breast cancer cells." (PMID 37477531, 2023). "The new approach was applied to identify optimal CSI quantile biomarkers based on protein expression of Ki-67, PCNA, PD-L2, and PR in breast cancer tissue." (PMID 37481512, 2023). "Another cell-cycle specific antigen and proliferation marker in breast cancer is proliferating cell nuclear antigen (PCNA), having an important role in DNA replication." (PMID 36612320, 2023). "Immunohistochemical staining of PCNA has been used extensively in breast cancer diagnosis and prognosis." (PMID 35933325, 2022). "MCM2 is a sensitive biomarker for cancer cell proliferation in keeping with classical markers proliferating cell nuclear antigen (PCNA) and Ki-67, and performs even better in colorectal cancer, breast cancer, and esophageal squamous cell carcinoma (ESCC)." (PMID 36303105, 2022). "We also compared the model with a “meta‐PCNA” proliferation index that was reported to capture the prognostic ability of most published signatures of breast cancer." (PMID 35671075, 2022).
breast cancer (continued). "In contrast, studies on breast cancer show that the expression of PCNA poorly correlates with Ki67 expression, suggesting that the usefulness of PCNA as a marker of proliferative activity appears to be limited." (PMID 36077614, 2022). "For example, the MCM proteins and PCNA are prolific markers for breast cancer and are participants in DNA replication." (PMID 35567389, 2022). "For example, SNHG5 can promote the proliferation and cell cycle progression of breast cancer cells by stimulating the overexpression of proliferating cell nuclear antigen (PCNA)." (PMID 35855425, 2022). "In the second, the gender, age, Ki67, COX-2, PCNA, PR and Her 2 were included in the lymphatic metastasis assessment of breast cancer in this study." (PMID 35372007, 2022). "It has been shown that targeting the EGFR/PCNA signalling suppresses tumour growth of triple-negative breast cancer cells and inhibit cancer growth in neuroblastoma and breast cancer mouse xenograft models." (PMID 35933325, 2022). "For example, RFC1 interacts with proliferating cell nuclear antigen (PCNA) to promote breast cancer cell survival." (PMID 35210438, 2022). "It has been shown that the deletion of function caused by the hypermethylation of the Cosmc promoter increases the expression levels of the proliferative genes Ki67 and proliferating cell nuclear antigen (PCNA) in breast cancer (BC) cells." (PMID 36551160, 2022). "The IHC staining with anti-PCNA, anti-ErbB2, and anti-caspase-3 detected PCNA, ErbB2, and caspase-3-positive cells, respectively, in the rat mammary tumors." (PMID 34164110, 2021). "Accordingly, a more pronounced proliferating activity was found in our untreated breast tumor, which correlates with the findings of other clinical studies that demonstrated PCNA is greatly involved in breast cancer initiation and development." (PMID 33986437, 2021). "We further confirmed our observations using immunofluorescence and observed more cytoplasmic PCNA in neutrophils treated with the supernatant of the breast cancer cells than those treated with SF media." (PMID 33049964, 2020). "All of five genes have been previously reported to have prognostic roles in several cancers, such as AARS in breast cancer and PCNA in colon adenocarcinoma." (PMID 32704448, 2020). "We observed more cytoplasmic-PCNA in the cytoplasm of neutrophils treated with breast cancer cell supernatants than those treated with SF media." (PMID 33049964, 2020). "In contrast, the proliferation marker cyclin D1/2 was even reduced at higher concentrations in all 3 cell lines and CDK4 in the two breast cancer cell lines whereas PCNA levels stayed unaffected." (PMID 32292575, 2020). "As for the PCNA gene, which has an important role in controlling DNA replication, it was found to be involved in many cancer types: in breast cancer, for example, PCNA methylation was found to be cancer specific." (PMID 33148191, 2020). "Proliferative cells, marked by Ki67 and PCNA, were also largely localized to the breast cancer tumor nests." (PMID 32445299, 2020). "As a critical pathological indicator of patients with breast cancer, Ki-67 is a proliferating cell nuclear antigen that is closely related to the period of mitosis." (PMID 30902883, 2019). "Cellular IF assay also showed that EYA2 overexpression enhanced the protein abundance of YBX1, EGFR, and PCNA in both breast cancer cell lines." (PMID 30761270, 2019). "PCNA is known as a marker for breast cancer, even if this should be verified at the protein level, considering that we analyzed only gene expression data." (PMID 31825969, 2019). "Western blotting showed that EYA2 overexpression induced the up-regulation of YBX1, EGFR, cyclin E, and PCNA in both these two breast cancer cell lines." (PMID 30761270, 2019).